KAT6A (lysine acetyltransferase 6A)
Diseases named in the same sentence as KAT6A in open-access papers (continued):
Sharing a sentence is not in itself a finding about the gene and the disease.
leukemia (26 papers, 2013 to 2025). A malignant (clonal) hematologic disorder, involving hematopoietic stem cells and characterized by the presence of primitive or atypical myeloid or lymphoid cells in the bone marrow and the blood. "To confirm the genomic associations among the NURF complex, KAT6A chimeras, and H3K4me2/3 in leukemia cells, we conducted CUT&RUN and ChIP-seq analyses in K/C-III leukemia cells." (PMID 40830799, 2025). "The remaining unremitted children included one with DEK::NUP214, one with secondary leukemia associated with KAT6A::CREBBP, and another with AXSL1 and SRSF2." (PMID 41264489, 2025). "Gene set enrichment analysis (GSEA) of murine K/C and K/P leukemia cells showed significant enrichment of the KAT6A-rearranged AML signature." (PMID 40830799, 2025). "Collectively, these results highlight the critical role of the NURF complex, via BPTF, in mediating the genomic targeting of KAT6A chimeras in leukemia cells." (PMID 40830799, 2025). "Together, these findings underscore the critical oncogenic dependency of KAT6A-rearranged leukemia on BPTF and CBP/P300." (PMID 40830799, 2025). "In summary, we established murine leukemia models for large KAT6A fusions and characterized their morphological, immunophenotypic, and transcriptomic features." (PMID 40830799, 2025). "KAT7 dysregulation is associated with a variety of cancers and, similar to KAT6A, KAT7 chromosomal translocations cause leukaemia." (PMID 37275850, 2023). "Both KAT6A and KAT7 are promising targets for anti-cancer therapy, in particular leukaemia, and a drug inhibiting the enzymatic activity of KAT6A is in clinical trials." (PMID 37275850, 2023). "Related to human disease, BRPF1/KAT6A/KAT6B mutations have all been identified as the cause of neurodevelopmental disorders, leukemia and other types of cancer." (PMID 36077605, 2022). "To further characterize the role of Brd9&Jmjd6 and Kat6a&Jmjd6 in leukemia, we performed RNA-seq to compare the global transcriptional changes upon either single or double genetic perturbation of the targeted genes." (PMID 32661245, 2020). "This screen reveals synthetic sick interactions between Brd9&Jmjd6, Kat6a&Jmjd6, and Brpf1&Jmjd6 in leukemia cells." (PMID 32661245, 2020). "To determine whether the menin-MLL interaction is essential in KAT6A-rearranged leukemia, we evaluated the therapeutic potential of Revumenib, a clinical-stage menin-MLL inhibitor effective in MLL-rearranged AML." (PMID 40830799, 2025). "Analysis of key factors, including Pol II, H3K27ac, BPTF, K/C, and MLL, in K/C-III leukemia cells revealed that A485 treatment for 6 h significantly decreased chromatin accessibility, Pol II loading, and the recruitment of the KAT6A-NURF-MLL module at Nup153 and Hoxa cluster loci." (PMID 40830799, 2025). "Even partial blockage of KAT6A reduced proliferation of myc-induced lymphoma and leukemia." (PMID 32877461, 2020). "Proscillaridin A induced a rapid loss of MYC protein expression in MYC-driven leukemia cells through the downregulation of series of KATs (KAT2A, KAT3A, KAT3B, KAT5 and KAT6A) known to be involved in MYC protein stability (by lysine acetylation) and activation of MYC transcriptional programs." (PMID 31196146, 2019). "The human KAT6A and KAT6B genes mutated recurrently in leukemia, nonhematologic malignancies, and multiple developmental disorders." (PMID 37365518, 2023). "KAT6A and KAT6B were originally identified as genes rearranged in leukemia." (PMID 36077605, 2022). "In addition, the KAT6A (NM_006766.4), also known as the MOZ or MYST3 gene, is recurrently rearranged or amplified in leukemia and non-hematologic malignancies, as well as involved in developmental disorders." (PMID 36672906, 2023).
acute myeloid leukemia (25 papers, 2008 to 2025). Acute myeloid leukemia (AML) is a group of neoplasms arising from precursor cells committed to the myeloid cell-line differentiation. "The KAT6A gene was identified as a common locus of chromosomal translocations associated with acute myeloid leukemia (AML)." (PMID 36553567, 2022). "Some animal studies on acute myeloid leukemia have been carried out to identify inhibitors of KAT6A that induce senescence and arrest growth in lymphoma." (PMID 36770785, 2023). "The histone acetyltranferase monocytic leukemia zinc finger protein (MOZ; MYST3 or KAT6A) is a key regulator of hematopoiesis recurrently found translocated in acute myeloid leukemia 1–5." (PMID 24307508, 2014). "KAT6A-CBP (K/C) and KAT6A-P300 (K/P) fusions are recurrent genetic alterations in acute myeloid leukemia (AML) associated with poor prognosis." (PMID 40830799, 2025). "KAT6A (MOZ, monocytic leukaemia zinc finger gene) was originally identified in an aggressive form of acute myeloid leukaemia resulting from a translocation fusing it to KAT3A24." (PMID 40000651, 2025). "KAT6A, which is a HAT that is specific for histone H3 acetylation, was first identified in acute myeloid leukaemia in 1996." (PMID 38956695, 2024). "Even a partial blockage of KAT6A can help reduce the proliferation of MYC-induced lymphoma and acute myeloid leukemia." (PMID 36770785, 2023). "Monocytic leukemia zinc finger protein (MOZ, also known as KAT6A) is a MYST family acetyltransferase, which was first discovered as a fusion partner of CBP in acute myeloid leukemia (AML) patients." (PMID 36712963, 2022). "This approach was used before to detect the fusion transcripts KAT6A-CREBBP and CIC-DUX4 as well as a novel alternative transcript of CSF1 in an acute myeloid leukemia, a small round cell sarcoma, and tenosynovial giant cell tumors, respectively." (PMID 25621995, 2015). "Molecular dysregulation of KAT6A and KAT6B has been observed in various tumor diseases, including solid tumors of the breast, lung, and ovary, as well as hematological tumors such as acute myeloid leukemia (AML)." (PMID 41357671, 2025). "Interestingly, MORF/MYST4 (KAT6B) is also involved in acute myeloid leukemia and the myelodysplastic syndrome with fusion to the CREB-binding protein (CBP) instead of p300, similar to that exhibited by MYST3/KAT6A." (PMID 33532133, 2021). "Translocations involving KAT6A (and KAT6B) is are identified in acute myeloid leukemia." (PMID 32877461, 2020). "Also groups of KAT6A- and NPM1-fusions are known in adult acute myeloid leukemia." (PMID 38086945, 2024).
Arboleda-Tham syndrome (15 papers, 2017 to 2026). "Heterozygous variants in the KAT6A gene encoding the histone lysine acetyltransferase KAT6A (MOZ, MYST3) cause Arboleda-Tham syndrome, a cognitive impairment syndrome." (PMID 42081590, 2026). "Patients with KAT6A pathogenic variants have Arboleda-Tham syndrome (OMIM 616268), an AD disease characterized by microcephaly, hypertonia, cardiac anomalies, gastrointestinal reflux, feeding difficulties, failure to thrive, and developmental delay." (PMID 40225944, 2024). "The nature of the KAT6A variant and the clinical presentation of this patient align well with Arboleda-Tham syndrome." (PMID 40225944, 2024). "KAT6A (Arboleda-Tham) syndrome is a Mendelian disorder of the epigenetic machinery caused by pathogenic variants in the lysine acetyltransferase 6 A (KAT6A) gene." (PMID 38741077, 2024). "Arboleda-Tham syndrome caused by pathogenic variants in KAT6A (Lysine Acetyltransferase 6A; OMIM 601408) has been recently described as a new neurodevelopmental disorder." (PMID 36672906, 2023). "On the one hand, KAT6A is linked to autosomal dominant intellectual disability, craniofacial-anomalies-cardiac-defects syndrome, recently described as Arboleda-Tham syndrome (OMIM 616268)." (PMID 36672906, 2023). "De novo mutations in KAT6A have recently been associated with a syndrome mainly characterized by intellectual disability (autosomal dominant mental retardation 32; MIM # 616268)." (PMID 32041641, 2020). "Here, we present five new unrelated cases bearing four truncating mutations and one missense mutation in KAT6A, and we review the existing literature to expand the clinical delineation of KAT6A syndrome." (PMID 32041641, 2020). "On the other hand, two patients (one male and one female) had the same genetic diagnosis (mental retardation autosomal dominant 32, associated to a mutation of the KAT6A gene)." (PMID 30110963, 2018). "Pathogenic variants in one allele of the KAT6A gene encoding the histone acetyltransferase KAT6A (MOZ, MYST3) cause Arboleda-Tham syndrome (ARTHS), characterised by developmental delay, cognitive impairment, and autism-like behaviours." (PMID 41702672, 2026). "Arboleda-Tham syndrome (ARTHS), caused by likely pathogenic or pathogenic variants in the KAT6A gene, is characterized by developmental delay, distinctive facial dysmorphic features, and congenital cardiac anomalies." (PMID 41431654, 2025). "Arboleda-Tham Syndrome (ARTHS) is a rare genetic disorder caused by heterozygous, de novo mutations in Lysine(K) acetyltransferase 6A (KAT6A)." (PMID 37861717, 2023). "Clinical exome sequencing (CES) revealed the presence of a de novo variant c.3385C>T (p.Arg1129*) in KAT6A (ACMG class IV PVS1, PM2) in the patient with this complex phenotype, which led to the diagnosis of Arboleda-Tham syndrome (ARTHS; OMIM 616268)." (PMID 36672906, 2023). "Arboleda-Tham syndrome (ARTHS, MIM 616268) is a newly defined, rare genetic disease caused by a pathogenic variant of KAT6A (MIM 601408) with autosomal dominant inheritance." (PMID 34930245, 2021). "Arboleda-Tham syndrome (ARTHS; OMIM: 616268), alternatively termed KAT6A syndrome, is recognized as a rare autosomal dominant neurodevelopmental disorder caused by variants in the KAT6A gene (OMIM: 601408) located on chromosome 8p11.21." (PMID 41431654, 2025). "Arboleda-Tham syndrome (ARTHS), caused by a pathogenic variant of KAT6A, is an autosomal dominant inherited genetic disorder characterized by various degrees of developmental delay, dysmorphic facial appearance, cardiac anomalies, and gastrointestinal problems." (PMID 34930245, 2021). "Mutations in KAT6A, encoding a member of the MYST family of histone acetyl-transferases, were recently reported in patients with a neurodevelopmental disorder (OMIM: #616268, autosomal dominant mental retardation-32)." (PMID 31754438, 2017).
Arboleda-Tham syndrome (continued). "Indeed, exome sequencing identified a pathogenic single-nucleotide variant within KAT6A (OMIM *616268) exon 18, causing AD Arboleda-Tham syndrome (OMIM #616268) (data not shown)." (PMID 34925449, 2021). "KAT6A acetylates histones K3K9, H3K14, and H3K23, but the genomic regions affected in Arboleda-Tham syndrome have not been comprehensively studied." (PMID 36064314, 2022).
developmental delay (12 papers, 2017 to 2026). "Mutations in KAT6A (MYST3) were recently identified as a cause of syndromic developmental delay; truncating mutations in the transactivation domain of KAT6A are causative of intellectual disability syndromes and gastrointestinal complications." (PMID 36539894, 2022). "Clinical exome sequencing in four independent families identified de novo nonsense mutations in the gene KAT6A in all probands displaying significant developmental delay, microcephaly, and dysmorphism." (PMID 29898714, 2018). "In this report, we describe three siblings with intellectual disability (ID) or global developmental delay and a KAT6A heterozygous nonsense mutation, i.e., c.3070C>T (p.R1024*, ENST00000406337; chr8:41795056G>A on hg19)." (PMID 31754438, 2017). "The main symptoms in our cases involved ID and developmental delay with very limited verbal development, which is consistent with previous reports of patients with KAT6A mutations." (PMID 31754438, 2017). "In this report, we describe three siblings with ID or global developmental delay with a KAT6A heterozygous nonsense mutation that was potentially transmitted from one of their parents as a germline mosaicism." (PMID 31754438, 2017). "Mutations in KAT6A gene is known to cause a syndrome characterized by developmental delay, hypotonia, cardiac defects, microcephaly, specific facial features and early feeding problems." (PMID 28649320, 2017). "In this report, we describe three siblings with ID or global developmental delay caused by a KAT6A mutation." (PMID 31754438, 2017). "Exome sequencing in patients with syndromic features associated with developmental delay and intellectual disability has revealed several causative pathogenic variants of KAT6A that are involved in the regulation of transcriptional activity and gene expression." (PMID 34930245, 2021). "A year ago, mutations in KAT6A was shown to cause a syndrome characterized by developmental delay, hypotonia, early feeding problems, cardiac defects, microcephaly and specific facial features such as broad nasal tip, bitemporal narrowing, thin upper lip, low set ears." (PMID 28649320, 2017). "Line mutations in several KATs and KDACs, such as KAT6A, SMC3 (coding chromosome protein 3), and HDAC8 (coding histone deacetylase 8, SMC3 deacetylase), are related to developmental retardation, abnormalities, and mental disabilities." (PMID 32399051, 2020). "Here, we identified a novel likely pathogenic variant of KAT6A using whole exome sequencing (WES) analysis in an infant with a dysmorphic facial appearance, cleft palate, and minor cardiac malformations at the age of two months before a developmental delay was apparent." (PMID 34930245, 2021).
Intellectual disability (11 papers, 2015 to 2026). "Mutations in the KAT6A gene relating to developmental disorders with intellectual disability are also reported." (PMID 36768434, 2023). "Most patients with pathogenic KAT6A variants have intellectual disabilities and speech delays that range from mild to severe." (PMID 34930245, 2021). "Since 2015, around 80 cases of syndromic intellectual disability due to mutations at the KAT6A gene have been described in the literature, delineating a new syndrome with variable presentation." (PMID 32041641, 2020). "Pathogenic variants of the lysine acetyltransferase 6A or KAT6A gene are associated with a newly identified neurodevelopmental disorder characterized mainly by intellectual disability of variable severity and speech delay, hypotonia, and heart and eye malformations." (PMID 32041641, 2020). "In Family 17, WES trio analysis identified a de novo heterozygous VUS in KAT6A (NM_006766.5: c.2436+5G > C) in the proband (II‐1), a female presenting with hemiplegia, intellectual disability, and dental anomalies." (PMID 41523913, 2026). "In GMCK-RD, a number of novel genes have been identified, resulting in improved biological understanding of disease mechanisms and better patient care as exemplified by KAT6A (intellectual disability), SLC12A5 (epilepsy of infancy), and MIR140 (skeletal dysplasia)." (PMID 33726816, 2021). "Of note, most individuals with variants in DDX3X, KAT6A, and DYRK1A have moderate‐to‐severe intellectual disability and do not typically use verbal speech to communicate." (PMID 39846212, 2025).
glioblastoma (9 papers, 2020 to 2025). The most malignant astrocytic tumor (WHO grade IV). "In glioblastoma cells, H3K23ac generated by lysine acetyltransferase 6A (KAT6A, also known as MOZ and MYST3) is associated with TRIM24." (PMID 39456765, 2024). "The activation of the PI3K/AKT signaling pathway, regulated by the KAT6A complex, has been reported to promote tumorigenesis and the development of glioblastoma." (PMID 41357671, 2025). "Overexpression of KAT6A was observed across multiple glioblastoma cell lines, which enhanced cell proliferation, migration, and tumor growth, ultimately leading to worse survival outcomes." (PMID 41357671, 2025). "In glioblastoma, KAT6A expression increases PI3Kα levels through the binding of TRIM24 to H3K23Ac in the PIK3CA gene promoter." (PMID 40676628, 2025). "Although in glioblastoma, KAT6A controls PIK3CA gene expression through TRIM24 binding to this gene promoter, in this study, TRIM24 promoted cell survival by associating to PI3Kα protein, thereby increasing its stability." (PMID 40676628, 2025). "The first was based on the observation of KAT6A-induced TRIM24-mediated PIK3CA mRNA expression in glioblastoma." (PMID 40676628, 2025). "However, KAT6A mRNA levels are increased in glioblastoma samples compared to normal brain tissue, and KAT6A and has been shown to promote glioma cell proliferation via upregulation of PIK3CA expression and subsequent activation of PI3K/Akt signaling." (PMID 31914141, 2020). "KAT6A acetylates histone H3, activating PIK3CA transcription, thereby enhancing the PI3K/AKT signalling pathway and promoting glioblastoma development." (PMID 39778006, 2025). "In addition, the overexpression of KAT6A was demonstrated to enhance PI3K/AKT signaling and tumorigenesis in glioblastoma cells." (PMID 35681732, 2022).
glioma (6 papers, 2020 to 2025). A benign or malignant brain and spinal cord tumor that arises from glial cells (astrocytes, oligodendrocytes, ependymal cells). "The team assessed the influence of KAT6A energy on the expression of PIK3CA in glioma cells, and the result indicated that it effectively inhibited the expression of PIK3CA and the activation of the PIEK/AKT signaling pathway." (PMID 39947253, 2025). "They found that KAT6A enhanced PIK3CA expression in the gliomas model, further, it could activate PI3K/AKT signaling." (PMID 39947253, 2025). "It is known that KAT6A promotes the binding of H3K23ac to TRIM24 in glioma cells." (PMID 32677374, 2020).
lymphoma (6 papers, 2020 to 2025). A malignant (clonal) proliferation of B- lymphocytes or T- lymphocytes which involves the lymph nodes, bone marrow and/or extranodal sites. "Additional eight mutations that were significantly enriched in rHL/prHL affect genes that were previously associated with the progression of other lymphoma subtypes (e.g., PDGFRB, KAT6A, HGF, EPHB1, NSD2, PMS2)." (PMID 39992429, 2025). "In an animal study, inhibitors of KAT6A/B induced senescence and arrest in lymphoma growth." (PMID 32877461, 2020). "In contrast, CBP, KAT inhibitors discovered recently, and A485, p300 inhibitor, showed antiproliferative effects on lineage-specific tumor cell lines; however, KAT6A and KAT6B inhibitors induced cell senescence and inhibited mouse lymphoma growth." (PMID 32399051, 2020).
colon cancer (4 papers, 2021 to 2024). "Another study found that long noncoding RNA (lncRNA) DANCR binds with KAT6A to affect the acetyltransferase activity of KAT6A, thereby influencing the expression of KAT6A target genes to promote the development and progression of colon cancer." (PMID 35991554, 2022).